TFE3 (transcription factor binding to IGHM enhancer 3)
Description:
Transcription factor that acts as a master regulator of lysosomal biogenesis and immune response. Specifically recognizes and binds E-box sequences (5'-CANNTG-3'); efficient DNA-binding requires dimerization with itself or with another MiT/TFE family member such as TFEB or MITF. Involved in the cellular response to amino acid availability by acting downstream of MTOR: in the presence of nutrients, TFE3 phosphorylation by MTOR promotes its inactivation. Upon starvation or lysosomal stress, inhibition of MTOR induces TFE3 dephosphorylation, resulting in transcription factor activity. Specifically recognizes and binds the CLEAR-box sequence (5'-GTCACGTGAC-3') present in the regulatory region of many lysosomal genes, leading to activate their expression, thereby playing a central role in expression of lysosomal genes. Maintains the pluripotent state of embryonic stem cells by promoting the expression of genes such as ESRRB; mTOR-dependent TFE3 cytosolic retention and inactivation promotes exit from pluripotency (By similarity). Required to maintain the naive pluripotent state of hematopoietic stem cell; mTOR-dependent cytoplasmic retention of TFE3 promotes the exit of hematopoietic stem cell from pluripotency. TFE3 activity is also involved in the inhibition of neuronal progenitor differentiation (By similarity). Acts as a positive regulator of browning of adipose tissue by promoting expression of target genes; mTOR-dependent phosphorylation promotes cytoplasmic retention of TFE3 and inhibits browning of adipose tissue (By similarity). In association with TFEB, activates the expression of CD40L in T-cells, thereby playing a role in T-cell-dependent antibody responses in activated CD4(+) T-cells and thymus-dependent humoral immunity (By similarity). Specifically recognizes the MUE3 box, a subset of E-boxes, present in the immunoglobulin enhancer. It also binds very well to a USF/MLTF site. Promotes TGF-beta-induced transcription of COL1A2; via its interaction with TSC22D1 at E-boxes in the gene proximal promoter (By similarity). May regulate lysosomal positioning in response to nutrient deprivation by promoting the expression of PIP4P1.
Synonyms: bHLHe33; TFEA; MRXSPF; RCCP2; RCCX1
Tractability: PROTAC: UniProt records ubiquitination sites on it; ubiquitination databases record sites on it.
Target class: Transcription factor
Gene: Protein-coding gene on chromosome X (49,028,726 to 49,043,476, reverse strand). Ensembl gene ENSG00000068323.
Subcellular location: Cytoplasm, cytosol; Nucleus; Lysosome membrane
Subcellular location (Human Protein Atlas): Cytosol; Nucleoplasm
Pathways (Reactome):
Developmental Biology: Transcriptional and post-translational regulation of MITF-M expression and activity
Gene Ontology:
Molecular function: DNA-binding transcription factor activity; DNA-binding transcription factor activity, RNA polymerase II-specific; protein binding; sequence-specific double-stranded DNA binding; RNA polymerase II cis-regulatory region sequence-specific DNA binding; transcription cis-regulatory region binding; DNA-binding transcription activator activity, RNA polymerase II-specific; protein dimerization activity
Biological process: lysosome organization; positive regulation of cell adhesion; positive regulation of DNA-templated transcription; positive regulation of transcription by RNA polymerase II; humoral immune response; negative regulation of cold-induced thermogenesis; positive regulation of brown fat cell differentiation; regulation of transcription by RNA polymerase II; regulation of DNA-templated transcription; regulation of osteoclast differentiation
Cellular component: cytoplasm; cytosol; lysosomal membrane; nucleoplasm; nucleus; chromatin
Cancer hallmarks: change of cellular energetics (promotes)
Homologues: Orthologues: macaque TFE3 (99% identical), pig TFE3 (97% identical), rabbit TFE3 (97% identical), dog TFE3 (96% identical), mouse Tfe3 (96% identical), rat Tfe3 (95% identical), guinea pig TFE3 (95% identical), chimpanzee TFE3 (61% identical), tropical clawed frog tfe3 (54% identical), zebrafish tfe3a (53% identical), zebrafish tfe3b (45% identical), Drosophila melanogaster Mitf (31% identical), and 1 more. Paralogues in human: MITF (48% identical), TFEB (37% identical), TFEC (26% identical).
Diseases named in the same sentence as TFE3 in open-access papers:
TFE3 is named in the same sentence as 192 diseases in open-access papers, as found by Europe PMC text mining. Sharing a sentence is not in itself a finding about the gene and the disease. The quoted sentences say what the papers report.
renal cell carcinoma (168 papers, 2007 to 2026). "TFE3‐rearranged renal cell carcinoma (TFE3‐RCC) lacks clearly defined diagnostic and therapeutic targets." (PMID 41199339, 2026). "TFE3-associated Xp11 translocations have also been observed in clear cell carcinoma and renal cell carcinoma." (PMID 40176092, 2025). "A significant update in this edition is the inclusion of a new category for molecularly defined renal neoplasms, such as TFE3-rearranged renal cell carcinoma and ELOC-mutated RCC." (PMID 41463280, 2025). "TRIM28 facilitates the ubiquitination and degradation of TFE3, hence preventing the growth of cells that cause renal cell carcinoma." (PMID 39534556, 2024). "Renal cell carcinoma (RCC) with TFE3 gene fusion caused by Xp11.2 translocations is a rare RCC subtype." (PMID 38953008, 2024). "Renal cell carcinoma (RCC) caused by Xp11.2 translocation/TFE3 gene fusion is an uncommon RCC subtype that was first identified by the World Health Organization (WHO) in 2004." (PMID 38953008, 2024). "The aggressiveness of renal cell carcinoma (RCC) associated with Xp11.2 translocation/TFE3 gene fusion (Xp11.2 translocation RCC [Xp11.2 tRCC]) is age‐dependent, which is similar to the overall trend of reproductive endocrine hormones." (PMID 35452181, 2022). "Renal cell carcinoma (RCC) associated with Xp11.2 translocation/TFE3 gene fusions is a rare subtype of renal tumor." (PMID 36034832, 2022). "Xp11.2 translocation renal cell carcinoma (tRCC), involving transcription factor E3 (TFE3) gene fusions, is a rare and aggressive RCC variant when present in adults and has been recently recognized as a unique entity in RCC." (PMID 35203530, 2022). "Renal cell carcinoma (RCC) associated with Xp11.2 translocation/TFE3 gene fusion is a rare and new subtype of RCC and was classified by the WHO in 2004." (PMID 34917511, 2021). "Xp11.2 translocation renal cell carcinoma (RCC) is a rare type of RCC associated with balanced translocation of transcription factor E3 (TFE3) and other fusion partners." (PMID 32632879, 2021). "Renal cell carcinoma (RCC) associated with Xp11.2 translocation/TFE3 gene fusion (Xp11.2 translocation RCC) is a rare but aggressive type of renal tumor." (PMID 33004995, 2020). "The fusion or amplification of TFE3 has been identified with molecular events such as perivascular epithelioid cell tumours (PEComas) and renal cell carcinoma associated with Xp11.2 translocation." (PMID 32566457, 2020). "Tumors with TFE3 rearrangement include PEComa with TFE3-rearrangement, Xp11-associated renal cell carcinoma (now reclassified as MiT family translocation renal cell carcinoma), melanotic Xp11 neoplasm, and alveolar soft part sarcoma." (PMID 31103952, 2019). "Renal cell carcinoma (RCC) associated with Xp11.2 translocation/TFE3 gene fusion (Xp11.2/TFE3) is an uncommon subtype of RCC." (PMID 31892340, 2019). "Postoperative pathology revealed Xp11.2 translocations/TFE3 gene fusions associated with renal cell carcinoma with a size of 4∗3 cm." (PMID 29901594, 2018). "Xp11.2 translocation /TFE3 gene fusion associated renal cell carcinoma is usually diagnosed by pathological examination." (PMID 29901594, 2018). "Renal cell carcinoma associated with Xp11.2 translocations/TFE3 gene fusions is a rare subtype of renal cell carcinoma." (PMID 29901594, 2018). "The first choice for the treatment of renal cell carcinoma associated with Xp11.2 translocation/TFE3 gene fusion include radical nephrectomy, and renal hilar lymph node dissection should be performed at the same time if the patients have lymph node metastases." (PMID 29901594, 2018). "Tfe3-gene fusions can be causal for renal cell carcinomas, which also occur in tuberosclerosis due to mutations in Tsc1 or Tsc2 and in Bird-Hogg-Dubé (BHD) syndrome due to Flcn mutations." (PMID 23582324, 2013).
renal cell carcinoma (continued). "The recently recognized renal cell carcinomas (RCCs) associated with Xp11.2 translocations (TFE3 transcription factor gene fusions) are rare tumors predominantly reported in children." (PMID 19450277, 2009). "Renal cell carcinoma (RCC) associated with Xp11.2 translocation/gene fusion TFE3 is a rare subtype of kidney cancer that was classified in 2016 as belonging to the family of renal carcinomas with MiT gene translocation (microphthalmia-associated transcription factor)." (PMID 39851801, 2025). "Among malignant subtypes, clear cell renal cell carcinoma (ccRCC) showed distinct Vascular Architecture compared with papillary renal cell carcinoma(pRCC), chromophobe renal cell carcinoma(chRCC), and Xp11.2 translocation/TFE3 fusion-associated renal cell carcinoma(tRCC) (P < 0.01)." (PMID 41324744, 2025). "This included cases of pRCC (n = 8, comprising 4 type I and 4 type II), chRCC (n = 5), renal cell carcinoma associated with Xp11.2 translocation/TFE-3 gene fusion (n = 4), sarcomatoid carcinoma (n = 1), collecting duct carcinoma (n = 1), and eosinophilic papillary carcinoma (n = 2)." (PMID 38886684, 2024). "In addition, NRF-1 activity has also been associated with estrogen-induced breast carcinogenesis, and renal cell carcinoma where it regulates the expression of the TFE3 gene required for cellular energy metabolism during proliferation." (PMID 39742254, 2024). "Pathological examination revealed that the case was considered to be XP11.2 tanslocations/TFE3 gene fusions associated renal cell carcinoma with a size of 9× 8 × 8 cm, vascular region showed invasion of carcinoma, and left renal hilar lymph nodes were with metastases (2/2)." (PMID 29901594, 2018). "XP11.2 translocation /TFE3 gene fusion associated renal cell carcinoma showed a very low incidence." (PMID 29901594, 2018). "Interestingly, 15% of cases of renal cell carcinomas in which TFE3 gene fusions are detected is associated with prior exposure to chemotherapy." (PMID 22566752, 2012). "Hematoxylin-eosin staining revealed papillary architecture and clear or eosinophilic cytoplasm, and the diagnosis of renal cell carcinoma associated with Xp11.2 translocations/TFE3 gene fusion was made by the immunohistochemical determination of transcription factor E3 protein." (PMID 22738297, 2012). "One of the most common gene fusions is ASPSCR1::TFE3, and this fusion requires differential diagnosis from translocation-associated renal cell carcinoma (RCC)." (PMID 38872175, 2024). "Herein, we present a case in which axitinib successfully reversed primary resistance to anti-PD-1 therapy in a patient with renal cell carcinoma (RCC) associated with Xp11.2 translocation/transcription factor E3 gene fusion (Xp11.2/TFE3)." (PMID 34764951, 2021). "Renal cell carcinomas (RCCs) driven by TFE3 rearrangement or TFEB alteration (MiT-RCC) account for up to 40% of pediatric RCCs but are rare in adults." (PMID 41899560, 2026). "TFE3‐rearranged renal cell carcinoma (TFE3‐RCC) represents an aggressive subtype of renal cancer characterized by a poor prognosis, yet lacking clearly defined diagnostic and therapeutic targets." (PMID 41199339, 2026). "Previous studies have reported that 6RK73 suppresses oncogenic UCHL1 activation in breast cancer and delays the progression of renal cell carcinoma (RCC) associated with Xp11.2 translocation/TFE3 gene fusion, particularly PRCC-TFE3 tRCC7." (PMID 41584043, 2026). "Subsequent biopsy pathology and immunohistochemistry confirmed the presence of metastatic TFE3 translocation renal cell carcinoma." (PMID 40177240, 2025). "It is the most common type of renal cell carcinoma in children, with the most common translocation affecting the TFE3 gene located on Xp11.2." (PMID 39918792, 2025).
renal cell carcinoma (continued). "Notably, it is important to rationally interpret TFE3 rearrangements in the context of morphology, as TFE3 rearrangements are also seen in other tumors such as alveolar soft tissue sarcomas, Xp11.2 translocation-associated renal cell carcinomas, and perivascular epithelioid cell tumors." (PMID 39917171, 2025). "In a comprehensive TCGA case series examining renal cell carcinoma, researchers identified the TFE3/Xp11 translocation in 1.2% of RCC cases." (PMID 40177240, 2025). "Nuclear TFE3 positivity has also been observed in various tumors, including Xp11.2 translocation renal cell carcinoma, perivascular epithelioid cell tumors, and granular cell tumors." (PMID 40176092, 2025). "Tumor development often requires cellular adaptation to a unique, high metabolic state; however, the molecular mechanisms that drive such metabolic changes in TFE3–rearranged renal cell carcinoma (TFE3‐RCC) remain poorly understood." (PMID 39807625, 2025). "In TFE3-rearranged renal cell carcinoma (TFE3-rRCC), chromosomal breakage occurs consistently at the TFE3 gene locus." (PMID 41367616, 2025). "The malignant lesions included 21 papillary renal cell carcinomas (pRCC), 8 chromophobe renal cell carcinomas (chRCC), 4 Xp11.2 translocation/TFE3 gene fusion-related renal cell carcinomas (tRCC), and 153 clear cell renal cell carcinomas (cRCC)." (PMID 41324744, 2025). "Postoperative pathology confirmed the presence of Mit family (TFE3/Xp11) translocation renal cell carcinoma, immunohistochemistry is shown in." (PMID 40177240, 2025). "Other rare histological subtypes of renal cell carcinoma include collecting duct, medullary, mucinous tubular and spindle cell, and Xp11.2 translocation/TFE3." (PMID 40491617, 2025). "This graphical abstract illustrates the key metabolic changes in TFE3–rearranged renal cell carcinoma (TFE3‐RCC)." (PMID 39807625, 2025). "Due to the morphologic heterogeneity, several neoplasms, particularly those with clear cells and papillary architecture, can be mistaken for TFE3-rearranged renal cell carcinoma." (PMID 39410016, 2024). "Recently, other markers have been suggested for supporting the diagnosis of TFE3-rearranged renal cell carcinoma: TRIM63 detected by RNA in situ hybridization (RNA-ISH) and GPNMB (glycoprotein nonmetastatic B) detected by immunohistochemistry." (PMID 39410016, 2024). "Namely, if the TFE3 translocation occurs in a renal tubular stem cell, the neoplastic transformation will produce a renal cell carcinoma expressing PAX8 and CD10 (i.e., markers positive in the proximal tubule of the kidney)." (PMID 39410016, 2024). "TFE3-rearranged renal cell carcinoma (RCC) is a rare subtype of renal tumor that typically affects the pediatric age group." (PMID 39502747, 2024). "In this setting, while initially just accustomed to a subtype of renal cell carcinoma, currently classified as TFE3-rearranged renal cell carcinoma, TFE3 fusions have been identified in a few mesenchymal neoplasms of the kidney viewed as PEComas." (PMID 39410016, 2024). "For example, the occurrence of an SFPQ::TFE3 translocation in a PAX8-positive renal tubular stem cell will give rise to renal cell carcinoma, which has a 78%, 38%, and 44% chance of staining for CD10, cathepsin K, and HMB45, respectively." (PMID 39410016, 2024). "Compared with the more common renal cell carcinomas, TFE3-rearranged renal cell carcinoma showed higher stage and frequent lymph node metastases, and, as we previously reported, recurrences or metastases occurred within 24 months from surgical resection." (PMID 39410016, 2024). "Xp11.2 translocation/TFE3 gene fusion renal cell carcinoma (TFE3-RCC) is recognized as a distinct pathological tumor." (PMID 38261736, 2024). "Trying to shed light on the solution to this emerging conundrum, we will review in detail the clinical, pathological, and molecular data of TFE3-rearranged renal cell carcinomas and TFE3-rearranged renal PEComa." (PMID 39410016, 2024).